PAK4 (p21 (RAC1) activated kinase 4)
Diseases named in the same sentence as PAK4 in open-access papers (continued):
Sharing a sentence is not in itself a finding about the gene and the disease.
osteosarcoma (4 papers, 2015 to 2024). A usually aggressive malignant bone-forming mesenchymal neoplasm, predominantly affecting adolescents and young adults. "This study showed that the expression of PAK4 and the expression of PD-L1 are associated with a shorter survival of osteosarcoma patients." (PMID 39273017, 2024). "In this study, the expression of PAK4 was closely associated with the proliferation and invasiveness of osteosarcoma cells in both in vitro and in vivo." (PMID 39273017, 2024). "Immunofluorescence staining for PAK4 and PD-L1 in osteosarcoma cells showed a positive association between the expression of PAK4 and PD-L1." (PMID 39273017, 2024). "In this study, despite a small number of osteosarcoma cases, the expressions of PAK4 and PD-L1 were significantly associated with a shorter survival of osteosarcoma patients." (PMID 39273017, 2024). "In this study, there was a significant association between PAK4 and PD-L1 positivity in human osteosarcomas." (PMID 39273017, 2024). "PAK4 positivity indicated a 6.888-fold (95% confidence interval; 1.237–38.367) greater risk of death in the osteosarcoma patients." (PMID 39273017, 2024). "In this study, the PAK4-related invasiveness of osteosarcoma cells was associated with the expression of the molecules involved in the epithelial-to-mesenchymal transition (EMT)." (PMID 39273017, 2024). "Due to the association of PAK4 positivity with the survival of osteosarcoma patients receiving adjuvant chemotherapy, we investigated the effects of PAK4 on osteosarcoma under treatment with doxorubicin." (PMID 39273017, 2024). "Furthermore, the PAK4-mediated activation of the proliferation and invasiveness of osteosarcoma cells was associated with the expression of genes related to cell cycle regulation, apoptosis, and invasiveness." (PMID 39273017, 2024). "Therefore, we evaluated the association between PAK4 and PD-L1 in osteosarcoma cells." (PMID 39273017, 2024). "In conclusion, this study demonstrates that the high expressions of PAK4 and PD-L1 are indicators of a poor prognosis in osteosarcoma patients." (PMID 39273017, 2024). "PAK4 was involved in resistance to apoptosis under a treatment regime with doxorubicin for osteosarcoma." (PMID 39273017, 2024). "In the U2OS and KHOS/NP osteosarcoma cells, the knockdown of PAK4 significantly inhibited the proliferation of cells." (PMID 39273017, 2024). "In human osteosarcomas, immunohistochemical positivity for the expression of PAK4 (overall survival, p = 0.028) and PD-L1 (relapse-free survival, p = 0.002) were independent indicators for the survival of patients in a multivariate analysis." (PMID 39273017, 2024). "In conclusion, this study suggests that PAK4 is involved in the progression of osteosarcoma by promoting proliferation, invasion, and resistance to doxorubicin and stabilized PD-L1 from proteasomal degradation." (PMID 39273017, 2024). "Given the prognostic significance of PAK4 expression in osteosarcomas, this study assessed its impact on the proliferation and invasiveness of osteosarcoma cells." (PMID 39273017, 2024). "In osteosarcoma cells, the overexpression of PAK4 increased proliferation and invasiveness, while the knockdown of PAK4 suppressed proliferation and invasiveness." (PMID 39273017, 2024). "In our results, PAK4 expression was related to the survival of osteosarcoma patients who received adjuvant chemotherapy." (PMID 39273017, 2024). "In 23 osteosarcoma patients who received adjuvant chemotherapy, the expression of PAK4 (OS; p = 0.033, RFS; p = 0.016) and PD-L1 (OS; p = 0.029, RFS; p = 0.019) was significantly associated with both overall survival and relapse-free survival." (PMID 39273017, 2024). "In contrast, the peritumoral infiltration of CD8-positive cytotoxic cells was significantly decreased in mice that were implanted with PAK4-overexpressing KHOS/NP osteosarcoma cells." (PMID 39273017, 2024).
osteosarcoma (continued). "In this study, PAK4 overexpression was associated with resistance to the doxorubicin-mediated apoptosis of osteosarcoma cells, and osteosarcoma cells that induced the knockdown of PAK4 were sensitized to doxorubicin-mediated apoptosis." (PMID 39273017, 2024). "We tested the effects of PAK4 knockdown in MCF-7 (adenocarcinoma) or U2OS (osteosarcoma) on collective cell migration." (PMID 26068882, 2015). "Therefore, this study evaluated the roles of PAK4 and PD-L1 in the progression of osteosarcomas in 32 osteosarcomas and osteosarcoma cells." (PMID 39273017, 2024). "In addition, the knockdown of PAK4 significantly decreased the migration and invasion activity of osteosarcoma cells, while the overexpression of PAK4 significantly increased these activities." (PMID 39273017, 2024). "Additionally, PAK4 is involved in the progression of osteosarcoma by promoting proliferation, invasion, and resistance to anticancer therapies." (PMID 39273017, 2024). "Therefore, this study investigated the expression of PAK4 and PD-L1 in human osteosarcoma tissues and further evaluated the role of PAK4 in the progression of osteosarcomas in conjunction with the expression of PD-L1." (PMID 39273017, 2024). "However, further study is needed to evaluate the clinicopathological significance of the expression of PAK4 and PD-L1 in more osteosarcoma cases." (PMID 39273017, 2024). "In human osteosarcomas, PAK4 and PD-L1 were expressed in the cytoplasm and nuclei of tumor cells." (PMID 39273017, 2024). "PAK4 stabilized PD-L1 from proteasomal degradation in osteosarcoma cells." (PMID 39273017, 2024). "Therefore, this study suggests that PAK4 is important in the sustained expression of PD-L1 in osteosarcoma cells." (PMID 39273017, 2024). "Therefore, this study suggests that targeting the PAK4 might be a novel therapeutic approach for osteosarcoma patients with tumors expressing high levels of PAK4 and PD-L1." (PMID 39273017, 2024). "In addition to the involvement of PAK4 in resistance to apoptosis, PAK4 might be involved in the cancer microenvironment related to the immune evasion of osteosarcoma cells." (PMID 39273017, 2024). "Therefore, this study suggests that PAK4 might be involved in the progression of osteosarcomas by stimulating the EMT." (PMID 39273017, 2024). "In addition, as PAK4 is expressed in the cytoplasm and nuclei of osteosarcoma cells in human osteosarcoma tissue, the expression of PAK4 in osteosarcoma cells was seen in both the cytoplasm and nuclei of cells, and its localization did not change with doxorubicin treatment." (PMID 39273017, 2024). "The multivariate analysis revealed age (RFS; p = 0.020), M category of stage (OS; p = 0.011), PAK4 positivity (OS; p = 0.028), and PD-L1 positivity (RFS; p = 0.002) as independent indicators of a poor prognosis for the OS or RFS of osteosarcoma patients." (PMID 39273017, 2024). "Therefore, although there are limited reports on using PAK4 inhibition in the therapeutic approach to osteosarcoma, it is suggested that using an agent targeting PAK4 might be helpful for those in the poor prognostic group of osteosarcoma patients who express high levels of PAK4." (PMID 39273017, 2024). "A multivariate survival analysis was performed with the potential prognostic indicators of osteosarcomas: age, TNM stage, T category, N category, M category, and the expression of PAK4 and PD-L1." (PMID 39273017, 2024). "In U2OS osteosarcoma cells, the knockdown or overexpression of PAK4 did not significantly affect the level of PD-L1 mRNA, but the protein level of PD-L1 decreased with the knockdown of PAK4 and increased with the overexpression of PAK4." (PMID 39273017, 2024). "Therefore, although we did not evaluate IDO1 expression in osteosarcoma, there may be crosstalk between PAK4 and IDO1, which could represent a novel therapeutic target in human cancers." (PMID 39273017, 2024).
rhabdomyosarcoma (4 papers, 2021 to 2023). A rare aggressive malignant mesenchymal neoplasm arising from skeletal muscle. "A previous study demonstrated that PAK4 plays a key role in Ras signaling, which contributes to the aggressive malignant phenotypes of rhabdomyosarcoma." (PMID 36523634, 2022). "In rhabdomyosarcoma (RMS), analysis of transcriptomic data from RMS tumors treated with and without a PAK4 inhibitor illustrated that GTPase/Ras signaling, as well as Notch and Hedgehog signaling, were downregulated when PAK4 was inhibited." (PMID 36594908, 2021).
triple-negative breast carcinoma (4 papers, 2017 to 2025). An invasive breast carcinoma which is negative for expression of estrogen receptor (ER), progesterone receptor (PR), and human epidermal growth factor receptor 2 (HER2). "KPT-8752 or KPT-9274 treatment of SUM159 cells, a triple negative breast cancer cell line, reduced PAK4 protein substantially after 72 h of treatment." (PMID 28198380, 2017). "We find that KPT-9274 (and its analog, KPT-8752) can reduce the steady state level of PAK4 protein in triple negative breast cancer cells." (PMID 28198380, 2017). "In particular, our previous work indicated that siRNA knockdown of PAK4 in the triple negative breast cancer cell line MBA-MB-231 reversed many aspects of tumorigenesis." (PMID 28198380, 2017). "In addition to SUM159 cells, KPT-9274 also reduced PAK4 protein in two other triple negative breast cancer cell lines; MDA-MB-231 and MDA-MB-468 cells, which was most noticeable after 48–72 hours of treatment." (PMID 28198380, 2017). "Thus, our results indicate that orally administered KPT-9274 reduces the steady state level of PAK4 protein and is capable of reducing growth of the triple negative breast cancer cells MDA-MB-231, MDA-MB-468 and SUM159." (PMID 28198380, 2017).
diabetes (3 papers, 2019 to 2024). "MODY is monogenic diabetes caused by a single gene mutation of either HNF-1α, HNF-1β, HNF-4α, HNF-1β, glucokinase, PAK4, KLF11, neurogenic differentiation 1 (neuroD1), and insulin (INS)." (PMID 35956399, 2022). "For instance, the roles of CREB and CRTC2 in diabetes mellitus have been extensively studied, suggesting the involvement of the PAK4-CRTC-CREB pathway in the pathogenesis of diabetes mellitus." (PMID 30755582, 2019). "Other diabetes-related genes, such as FGFR3, MTA3, PAK4, and KIF22, had similar results." (PMID 39000600, 2024).
esophageal squamous cell carcinoma (3 papers, 2017 to 2022). Esophageal squamous cell carcinoma (ESCC) is a type of esophageal carcinoma (EC) that can affect any part of the esophagus, but is usually located in the upper or middle third. "PAK4 has been previously shown to be overexpressed in human esophageal squamous cell cancers compared to paired normal esophageal epithelium." (PMID 29983868, 2018).
Obesity (3 papers, 2022 to 2026). Accumulation of substantial excess body fat. "These insights collectively support the therapeutic potential of targeting PAK4 in obesity, type 2 diabetes and metabolic dysfunction-associated steatotic liver disease." (PMID 41735496, 2026). "Therefore, we hypothesized that MYH10, PAK4, and PIKfyve might be the targets of obesity-induced cognitive impairment, providing new ideas, and directions to understand the pathogenesis of obesity-induced cognitive impairment." (PMID 36408417, 2022).
pancreatic adenocarcinoma (3 papers, 2017 to 2023). "Three genes (MAP2K2, RAC3, and PAK4) that were conserved in the SSCs of all three primates were also involved in numerous pathways, including “Pancreatic adenocarcinoma pathway”, “Integrin-mediated Cell Adhesion”, “Regulation of Actin Cytoskeleton”, and “Ras signaling”." (PMID 36902187, 2023).
pancreatic neuroendocrine tumor (3 papers, 2019 to 2025). Pancreatic endocrine tumor, also known as pancreatic neuroendocrine tumor (PNET), describes a group of endocrine tumors originating in the pancreas that are usually indolent and benign, but may have the potential to be malignant. "In conclusion, our study illustrates the therapeutic potential of PAK4-NAMPT dual inhibition as a feasible strategy for the difficult to treat pancreatic neuroendocrine tumors." (PMID 31795447, 2019). "Notably, a real-world study on pancreatic neuroendocrine tumors (a shared neuroendocrine malignancy) demonstrated that PAK4 overexpression correlates with adverse prognosis, and pharmacological inhibition of PAK4 significantly suppresses tumor progression." (PMID 40708824, 2025). "Recently KPT-9274, an inhibitor of nicotinamide phosphoribosyltransferase (NAMPT) and p21-activated kinase 4 (PAK4), was found active in pancreatic neuroendocrine tumors and is currently being evaluated in a human phase 1 study in patients with advanced solid malignancies." (PMID 37894327, 2023).
renal cell carcinoma (3 papers, 2016 to 2022). "PAK4 is present in pathways for renal cell carcinoma, ErbB signaling, focal adhesion, T-cell receptor signaling, and regulation of the actin cytoskeleton." (PMID 27788148, 2016). "The PAK4-inhibitor KPT-9274 has been shown to have efficacy in renal cell cancer lines." (PMID 29983868, 2018). "Moreover, application of PAK4 inhibitors in renal cell carcinoma (RCC) has been reported as well." (PMID 36105226, 2022).
thyroid cancer (3 papers, 2017 to 2019). "Furthermore, the expression of several genes, such as GRIM-19, CXCL12, and PAK4, is associated with not only the development of thyroid cancer but also the pathogenesis of adenomyosis." (PMID 29522577, 2018). "More significantly, independent studies have shown that MAPK and AKT activated thyroid cancers are responsive to PAK4 inhibition." (PMID 31905765, 2019). "Furthermore, TSH-induced increase in PAK4 activity was found to promote the invasive potential of thyroid cancer cells, thereby identifying a novel role of TSH signaling in prognosis of PTC." (PMID 28178642, 2017). "Furthermore, PAK4 overexpression has been detected in thyroid cancer, cell lines derived from breast, prostate, gall bladder, stomach and ovarian cancers, as well as in several primary tumors." (PMID 28178642, 2017). "Among the group I PAKs, siRNA-mediated knockdown of only PAK1 reduced migration significantly in thyroid cancer cell lines, but an additional role for PAK4 was not excluded." (PMID 28178642, 2017).
diffuse large B-cell lymphoma (2 papers, 2021 to 2022). "PAK4 was highly expressed in NHL (Diffuse large B-cell lymphoma) primary tumor tissue (n = 94) vs. normal lymph nodes (n = 8)." (PMID 35008323, 2021). "KPT–9274 is recognized as a dual inhibitor of PAK4 and NAMPT, which is capable of effectively inhibiting the growth of mantle cell lymphoma, follicular lymphoma, and diffuse large B-cell lymphoma." (PMID 35800076, 2022).
Ewing sarcoma (2 papers, 2021). A small round cell tumor that lacks morphologic, immunohistochemical, and electron microscopic evidence of neuroectodermal differentiation. "Finally, future studies could include an investigation into the role of PAK4 and immune evasion in Ewing sarcoma." (PMID 36594908, 2021).
head and neck cancer (2 papers, 2020 to 2024). A primary or metastatic malignant neoplasm affecting the head and neck. "In addition, PAK4 was remarkedly downregulated in head and neck cancer analyzed by starBase." (PMID 32041570, 2020).
pancreatitis (2 papers, 2017 to 2025). Inflammation of the pancreas. "The studies of physiological/pathological function show that PAK2 and PAK4 are involved in secretory function and activating the central growth signaling cascade involving the MAPK cascade and that PAK2 activation plays an essential role in the induction of pancreatitis." (PMID 40001881, 2025).
papillary thyroid cancer (2 papers, 2017 to 2019). "In a recent study PAK4 was shown to be involved in TSH induced papillary thyroid cancer cell proliferation." (PMID 31905765, 2019). "Here, we identified a role for PAK4 in papillary thyroid cancer progression." (PMID 28178642, 2017). "Although p21-activated kinase 4 (PAK4) is involved in the development of different types of tumor, its function has not been investigated in papillary thyroid cancer." (PMID 28178642, 2017).
Sepsis (2 papers, 2020 to 2021). Sepsis is defined as life-threatening organ dysfunction caused by a dysregulated host response to infection. "Notably, this study showed that GPR43 induced PAK4 and PPARγ protein expressions and suppressed Nox1 protein expression in macrophage by LPS+ATP or mice model of sepsis." (PMID 34584017, 2021).
skin cancer (2 papers, 2016 to 2022). "Similar increase of PAK4 protein is observed in thyroid, stomach, pancreatic, and skin cancers as well." (PMID 36105226, 2022). "Especially, all patients suffering from thyroid cancer or skin cancer have medium to high PAK4 expression." (PMID 36105226, 2022). "Furthermore, over 80% of patients bearing thyroid, colorectal, pancreatic, testis, and skin tumors have medium to high expression of PAK4 protein." (PMID 36105226, 2022). "Moreover, in skin cancer specifically, PAK1 and PAK4 promote cell invasion of uveal melanoma and SCC cell lines, respectively." (PMID 27765920, 2016).
acute lung injury (1 paper, 2017). A condition of lung damage that is characterized by bilateral pulmonary infiltrates (pulmonary edema) rich in neutrophils, and in the absence of clinical heart failure. "In summary, PAK4 is a key regulator in the pathophysiological process of acute lung injury (ALI) and can be a useful target for ALI treatment." (PMID 29445744, 2017).
acute pancreatitis (1 paper, 2025). An acute inflammatory process that leads to necrosis of the pancreatic parenchyma. "The possibility that the activation of group II PAKs (PAK4) could also be important in the pathogenesis of acute pancreatitis was suggested by a study using the in vitro model of acute pancreatitis by administering taurolithocholic acid to the pancreatic acinar cell line, AR42J cells." (PMID 40001881, 2025).
anaplastic thyroid cancer (1 paper, 2019). "In conclusion, our studies bring forward two novel targets XPO1 and PAK4 as actionable therapeutic avenues to overcome resistance to lenvatinib in refractory anaplastic thyroid cancer." (PMID 31905765, 2019). "We next explored the impact of targeting nuclear exporter protein XPO1 and Rho GTPase effector PAK4 either alone or in combination with lenvatinib in anaplastic thyroid cancer cells." (PMID 31905765, 2019). "Since, IPA-3 selectively inhibits PAK1 and does not cause inhibition of groups II PAKs (including PAK4), these results suggest that while targeting PAK4 in anaplastic thyroid cancer cells is a viable option, targeting PAK1 is not." (PMID 31905765, 2019). "Furthermore, we showed that targeted inhibition of XPO1 and PAK4 could sensitize anaplastic thyroid cancer cells to lenvatinib." (PMID 31905765, 2019). "Therefore, it may be envisaged that targeting XPO1 by SINE or PAK4 by KPT-9274 may serve to reduce the dose and frequency of lenvatinib regimen required to achieve therapeutic effects in anaplastic thyroid cancer." (PMID 31905765, 2019).
aneuploidy (1 paper, 2019). Chromosomal disorder consisting of the presence a chromosomal abnormality in which there is an addition or loss of chromosomes within a set. "We hypothesized that PAK4 inhibition may generate less force generated by the microtubules, which mechanically exerts less pull tension on the kinetochores of homologous chromosomes, thereby resulting in the disorder of K-T attachment and eventually producing aneuploidy." (PMID 31595158, 2019).
Atrophy (1 paper, 2025). Any weakening or degeneration, especially through lack of use. "PGC‐1α protein levels were downregulated in both mouse models of muscle atrophy but were restored by PAK4 inhibition (via genetic KO or PROTAC)." (PMID 41328324, 2025).
biphasic mesothelioma (1 paper, 2023). "PAI1 and PAK4 may be useful in the diagnosis of biphasic mesothelioma since they are frequently expressed in the sarcomatoid portion." (PMID 37761312, 2023).